TNF (tumor necrosis factor)
Diseases named in the same sentence as TNF in open-access papers (continued):
Sharing a sentence is not in itself a finding about the gene and the disease.
uveitis (continued). "More recently, animal models and corroborative human evidence support the role of tumour necrosis factor α (TNF-α) in the aetiopathogenesis of uveitis and, moreover, the potential value of inhibiting TNF-α as a therapeutic intervention." (PMID 24405833, 2014). "Several cases of new onset uveitis or uveitis relapses have been reported during anti-TNFα treatment, while the other articular manifestations where controlled by the therapy." (PMID 24991219, 2014). "It is widely accepted that multiple cytokines, chemokines, and adhesion molecules, such as TNF-α, MCP-1, RANTES, fractalkine, iNOS, and ICAM-1, are implicated in the pathogenesis of uveitis." (PMID 25147441, 2014). "One theory for ETA-associated uveitis is that, when the soluble receptor ETA binds with TNFα, it prevents the clearance of TNFα and prolongs its half-life and thus the presence within the eye structures." (PMID 24991219, 2014). "Translating these data to humans, several case series have been published that have demonstrated the efficacy of anti-TNF-α therapies, including infliximab and adalimumab, in the treatment of severe refractory uveitis in adults and children." (PMID 24405833, 2014). "In any case, uveitis is described also during therapy with the anti-TNFα antibodies and has also been successfully treated with ETA." (PMID 24991219, 2014). "Studies utilising experimental models of autoimmune uveitis have demonstrated that TNF-α plays a pivotal role in the pathogenesis of intraocular inflammation, which has been borne out in the treatment of adult uveitis." (PMID 24405833, 2014). "Adalimumab, when used as first anti-TNF-α treatment in chronic, refractory childhood uveitis, shows a better efficacy than used as second line anti-TNF-α agent." (PMID 23587261, 2013). "In a recent comparative cohort study on anti-TNF-α treatment for sight-threatening childhood uveitis, adalimumab was more efficacious than infliximab in maintaining remission of chronic childhood uveitis for over 3 years." (PMID 24489444, 2013). "In a study of Japanese patients, Th22 cells played an important role in enhancing the inflammatory response in patients with BD who have uveitis through producing large amounts of IL-22 and tumor necrosis factor-α (TNF-α)." (PMID 24049437, 2013). "Adalimumab is currently considered the most efficacious TNF-α blocker for childhood uveitis and the preferred biologic drug for the treatment of uveitis associated with JIA." (PMID 24489444, 2013). "The TNF-α inhibitors most commonly used for uveitis are infliximab, adalimumab, and less commonly etanercept." (PMID 23522744, 2013). "The role of tumor necrosis factor-alpha (TNF-α) inhibitors in the treatment of patients with uveitis is being investigated; these inhibitors appear to be more effective than corticosteroids in some patients with noninfectious uveitis." (PMID 24289205, 2013). "In contrast to these results, there exist multiple cases in the literature reporting the occurrence of uveitis following anti-TNF therapy." (PMID 23983404, 2013). "In another subsequent study based on a French survey, 31 cases of new onset of uveitis during treatment with anti-TNF blockers were reported." (PMID 23983404, 2013). "This would argue in favor of aggressive treatment early in a case of severe uveitis, with systemic corticosteroids and possibly anti-TNF-α blockade." (PMID 24289205, 2013). "Patients with uveitis were excluded, as there are opinions more favorable to Infliximab and Adalimumab (other anti-TNFα agents), or Abatacept (a cytotoxic T-lymphocyte antigen 4 fusion protein), in the treatment of JIA-associated uveitis." (PMID 23990845, 2013). "In recent evidence-based interdisciplinary guidelines for anti-inflammatory treatment of uveitis associated with JIA, adalimumab is recommended as the preferred TNF-α inhibitor." (PMID 24489444, 2013).
uveitis (continued). "Anti-mouse IL-17-blocking antibodies as well as anti-TNF-α antibody suppress intraocular inflammation in experimental uveitis models." (PMID 22546542, 2012). "Perez-Guijo and Santos-Lacomba reported that the concentration of TNF-α in the aqueous humor of uveitis patients were significantly higher than that of a normal control group." (PMID 22408441, 2012). "A new anti-TNF-α monoclonal antibody, infliximab, greatly suppresses ocular inflammation in uveitis patients with BD." (PMID 22546542, 2012). "GLM appears to be safe and provides an alternative treatment in refractory JIA uveitis, including patients who have failed other TNF inhibitors." (PMID 22581347, 2012). "Off-label use of biologic response modifiers such as tumor necrosis factor alpha (TNFα) inhibitors, including infliximab, adalimumab, and etanercept, have expanded the treatment armamentarium for refractory JIA-associated uveitis." (PMID 22581347, 2012). "Elevated levels of IL-1β and TNF-α in the vitreous and serum of patients with uveitis suggests that uveitis is driven by a systemic inflammatory response." (PMID 22389806, 2012). "The preferred anti-TNF-α agent is adalimumab, which is more effective against uveitis than etanercept and better tolerated by children." (PMID 22229035, 2012). "The proinflammatory cytokine TNF-α can promote Th17 differentiation in BD patients who have uveitis." (PMID 22546542, 2012). "In rats with endotoxin-induced uveitis, subcutaneous injection of Etanercept reduced the level of TNF-α and decreased intraocular inflammation." (PMID 22802951, 2012). "Taken together, the evidence indicates that TNF-α plays an important role in the etiology of uveitis." (PMID 22408441, 2012). "Of the TNF-α inhibiting therapies, etanercept is ineffective in controlling both the systemic symptoms of IBD and the associated uveitis." (PMID 22229035, 2012). "Preliminary safety studies to evaluate toxicity of intravitreal injection of TNFα inhibitors have been performed in rabbits with experimental uveitis, with promising results." (PMID 22229035, 2012). "A number of observational studies have shown the benefits of anti-TNF agents in the treatment of childhood uveitis." (PMID 22581347, 2012). "Biologic response modifiers, also known as biologics, are a newer class of therapeutic proteins used to treat uveitis by inhibiting bioactive mediators or cytokines such as tumor necrosis factor alpha (TNF-α) and interleukin-2." (PMID 23028205, 2012). "As shown in the current experiments, infliximab significantly suppressed IFN-γ, IL-6 and IL-17 inflammatory cytokines in addition to TNF-α produced by activated CD4+ T cells from BD patients who have active uveitis." (PMID 22546542, 2012). "TNF-α and other proinflammatory cytokines are produced by monocytes and T lymphocytes in BD uveitis patients, and these inflammatory cytokines are critical for the formation of inflammatory lesions, such as ocular lesions." (PMID 22546542, 2012). "This article provides a review of current literature on biologic agents, such as tumor necrosis factor blockers, anti-interleukins and other related biologics, such as interferon alpha, for the treatment of uveitis." (PMID 22454752, 2011). "In the last 10 years, anti-TNF drugs have been successfully utilized for the treatment of uveitis and have become a useful tool for clinicians." (PMID 22047067, 2011). "In these conditions, TNF-α represents one of the most important amplifying factors in inflammatory reactions; in case of uveitis, TNF-α is found at high concentrations both in the aqueous humor and in the serum, similar to RA17." (PMID 22454752, 2011). "LPS-induced uveitis is often accompanied by elevated expression of cytokines such as tumor necrosis factor-α (TNF-α), interleukin-6 (IL-6), monocyte chemoattractant protein-1 (MCP-1)." (PMID 22040935, 2011). "TNF-α is an inflammatory cytokine found in animal models of uveitis as well as the aqueous of eyes with uveitis." (PMID 20029145, 2010).
uveitis (continued). "On the basis of this observation, blocking TNF-α seems to be a promising approach in the therapy of uveitis." (PMID 21180427, 2010). "One of the recent breakthroughs in the treatment of refractory uveitis includes the introduction of immunomodulating drugs: Tumor necrosis factor-alpha antagonist and Interferon-alpha." (PMID 20029145, 2010). "Other reports have indicated that TNF-α concentrations in the aqueous humor increase before the clinical signs of uveitis can be observed." (PMID 20806043, 2010). "Perez-Guijo and Santos-Lacomba reported that the concentrations of TNF-α in the serum and aqueous humor of uveitis patients were significantly higher than those of a normal control group." (PMID 20806043, 2010). "Taken together, this evidence indicates that TNF-α plays an important role in the etiology of uveitis." (PMID 20806043, 2010). "The effect of anti-TNF-α treatment in uveitis is explained by increasing the fraction of peripheral CD4+ T cells expressing IL-10 with a recovery of visual function." (PMID 21180427, 2010). "TNF-α is a pleiotropic cytokine produced by a variety of cells that plays a primary role in uveitis pathogenesis." (PMID 21180427, 2010). "Uveitis was detected across all TNF-α inhibitors, with signal intensity varying by agent." (PMID 41329755, 2025). "A multicenter study involving 30 patients who met the international criteria for Behçet’s disease found that tocilizumab may be an effective alternative to anti-TNF agents in managing Behçet’s disease-related neurological symptoms and uveitis." (PMID 41367023, 2025). "Likewise, other case series have reported high success using anti-TNF-α agents in uveitis that previously required cyclophosphamide." (PMID 41286205, 2025). "Therapeutically, interventional human evidence now supports immunity as both driver and target: anti-VEGF re-seals leaky barriers, complement inhibition slows geographic atrophy, steroid implants suppress inflammatory oedema, and anti-TNF/IL-6R biologics improve refractory uveitis." (PMID 41394857, 2025). "Elevated TNF-α levels are also found in recurrent-pattern uveitis, suggesting that relapsing or refractory VKH disease may be associated with persistent TNF-α–driven inflammation." (PMID 41471337, 2025). "Elevated levels of IL-6 and TNF-α in uveitis patients may promote fibroblast activation and collagen deposition, leading to lacrimal duct fibrosis." (PMID 40687721, 2025). "In summary, the observed differences in uveitis prevention between etanercept and monoclonal TNF-α inhibitors likely arise from their selective binding to sTNF-α/mTNF-α, their differential blockade of receptor pathways, and variations in ocular drug distribution." (PMID 40621455, 2025). "In two patients (2%), TNF-α inhibitors were withdrawn due to the development of de novo uveitis." (PMID 41153616, 2025). "This study investigated the rates of uveitis recurrence and new-onset occurrence among patients with AS receiving TNFα inhibitors and examined whether there were differences among three different TNFi agents." (PMID 38337605, 2024). "Our findings suggest a lower risk of uveitis recurrence associated with anti-TNFα monoclonal antibodies, as opposed to an increased risk of recurrence or occurrence with etanercept, both in the short- and long-term periods." (PMID 38337605, 2024). "Average duration of uveitis prior to start of anti-TNF agents was two years (4 months-5 years)." (PMID 39078559, 2024). "TNF-α was quantified in uveitis patients’ aqueous humor and serum." (PMID 39407875, 2024). "A diverse array of cytokines, including IL-6, IL-4, IL-2, and IL-1, as well as intercellular adhesion molecule 1 (ICAM1), monocyte chemoattractant protein-1 (MCP-1), and tumor necrosis factor-α (TNF-α), are considered to be involved in the pathogenesis of uveitis." (PMID 39839649, 2024).
uveitis (continued). "Biologic medications, such as anti-TNFα agents, overlap in their use as treatment of both IBD and uveitis, and yet in some patients may also increase the risk of acute uveitis flares, as well as opportunistic, sight-threatening infections." (PMID 39767762, 2024). "Studies of serum cytokine levels in patients with noninfectious uveitis have consistently identified associations with elevated TNF-α, IL-6, IFN-γ and IL-17 A." (PMID 39075390, 2024). "There are two anti-TNF drugs most commonly used in the treatment of refractory uveitis." (PMID 38892808, 2024). "Treatment with a TNF-α blocker exhibited positive effects on various manifestations of uveitis." (PMID 39839649, 2024). "Interestingly, BU patients tend to respond better to anti-TNF-α agents compared to those with idiopathic uveitis." (PMID 38778397, 2024). "TNF-α, a cytokine that can be stimulated by signaling through Toll-like receptors or initiated by heightened concentrations of other cytokines, intensifies the degree of uveitis." (PMID 39839649, 2024). "Inhibition may be an effective treatment for the most severe cases of uveitis unresponsive to anti-TNF agents." (PMID 37700264, 2023). "The authors therefore postulate that the TNF-R might have a regulatory role in uveitis over and above just mopping up TNFα." (PMID 36652160, 2023). "As a TNF inhibitor, Infliximab (IFX) was first used for the treatment of refractory uveitis in BD over 20 years ago, and is currently the most frequently administered agent for BD-associated uveitis in Japan." (PMID 36744150, 2023). "It is also a predictive factor of the response to anti-TNF in axial forms and in uveitis." (PMID 37941856, 2023). "TNF-α inhibitors enabled complete control of uveitis after a median of 3 months." (PMID 36831165, 2023). "Female sex tended to be associated with a higher risk of non-persistence, and the presence of uveitis showed the trend of a lower possibility of TNF-α blockers’ withdrawal." (PMID 36986479, 2023). "Our results support a possible role of subcutaneous tocilizumab in anti-TNF refractory uveitis." (PMID 37700264, 2023). "Furthermore, in a multicentric French study, treatment with TCZ was associated independently with complete response of uveitic macular edema, one of the most fearsome manifestations of uveitis, compared with anti-TNF-α agents." (PMID 36979992, 2023). "In addition, previous researchers have found the increased expression of circulating CRP, IL-6, and TNF-α in the uveitis." (PMID 36275682, 2022). "In patients, TNF inhibitors have additionally exhibited promise for ocular diseases beyond uveitis." (PMID 35251042, 2022). "However, none of five studies included in a recent review on intravitreal administration of anti-TNFα agents to treat uveitis assessed ADAs." (PMID 35704329, 2022). "There are several hypotheses about the differences in the occurrence of uveitis between those taking anti-TNF-α monoclonal antibodies and those taking soluble TNF receptor (ETN)." (PMID 35160082, 2022). "Moreover, the downregulation of IL-35 expression at the peak of EAU also coincided with the upregulation of proinflammatory cytokines such as TNF-α and IL-6 that initiate and promote pathology in uveitis." (PMID 35897732, 2022). "Previous studies have shown that expressions of IL-6, IL-8, and TNF-α were higher in uveitis." (PMID 36242032, 2022). "The mean duration of uveitis evolution before the introduction of anti-TNFα was 16 months." (PMID 35311049, 2022). "Several studies have shown that TNF plays an important role in the onset of uveitis and glaucoma." (PMID 36530572, 2022). "On the other hand, a recent observational study reported that the risk of uveitis in patients with spondyloarthritis was higher with the use of ETN than of anti-TNF-α monoclonal antibodies, but the differences were not significant." (PMID 35160082, 2022).
uveitis (continued). "In line with our data, the EAU uveitis mouse model and a rabbit model for ocular inflammation using intravitreal injection of recombinant TNF-α also developed posterior synechiae, demonstrating that TNF-α leads to the development of synechiae also in non-rodent species." (PMID 35579886, 2022). "Distinct from anti-TNF-α monoclonal antibodies, ETN also has the capacity to efficiently bind and then release TNF-α, which may serve to prolong the circulating half-life of TNF-α, leading to prolonged intraocular TNF-α stimulating uveitis." (PMID 35160082, 2022). "In rats, CBD (Cannabidiol) has demonstrated inhibition of TNFα in experimentally induced uveitis as well as retinal TNFα release, which could be efficacious in management of autoimmune uveitis, retinal inflammation, and neuroprotection." (PMID 35998207, 2022). "With regard to biologics, anti-TNF-alpha intravenous chimeric monoclonal antibody (mAb) infliximab was the most frequently used in our study population since it was the first approved drug for uveitis." (PMID 35566597, 2022). "Adalimumab, a novel TNF-α inhibitor, has been proven to be effective in long-term remission of ocular inflammation, sparing systemic GCs, and rescue of visual acuity, mostly by experience and studies on uveitis." (PMID 36431163, 2022). "Indeed, TNF blockade with adalimumab, a monoclonal antibody, is clinically approved for the treatment of uveitis." (PMID 35251042, 2022). "Indeed, children in our study have a mean duration of uveitis evolution before introducing anti-TNFα of 16 months and a mean duration of oral steroid impregnation, during the 5-year follow-up, of 22 months, which is obviously too much." (PMID 35311049, 2022). "Hitherto, most reported studies were case series of ADA treatment in refractory BD-associated uveitis or retrospective controlled studies among different anti-TNF agents in the treatment of non-infectious uveitis." (PMID 34239438, 2021). "Notably, the YCU has a Behçet’s Disease Medical Research Center with experienced rheumatologists and ophthalmologists, prompting this trend because ophthalmology department of YCU had many severe BD uveitis patients and they were administered TNF inhibitors." (PMID 33522943, 2021). "In 1993, a team observed that TNF-α could protect against the inflammatory processes of endotoxin-induced uveitis (EIU)." (PMID 34795583, 2021). "To date, anti-TNF-α agents have made more progress for uveitis treatment." (PMID 34795583, 2021). "We may summarize that the upregulation of inflammatory cytokines plays an important role in the pathophysiology of uveitis, mainly IL-6, as well as IL-1β, IL-2, INFγ, TNFα, IL-10, and GM-CSF." (PMID 33921773, 2021). "Besides HLA-B27, other genes involving TNF, IL-17, and IL-23 pathways have been identified for uveitis, emphasizing the major role of inflammation in this disease." (PMID 34631754, 2021). "TNF-α results in uveitis after intravitreal injection into the rabbit eye." (PMID 34795583, 2021). "Although uveitis represents a group of intraocular inflammatory conditions, each with its own phenotypic heterogeneity, the commonality is the increased expression of TNF-α in both the serum and aqueous humor." (PMID 34795583, 2021). "This fact suggest that TAC could be a better option than DXM when the uveitis is related with an elevation of TNF-α." (PMID 34684030, 2021). "However, differently than other anti-TNF-α drugs, Adalimumab has been tested in three large randomized control trials for uveitis." (PMID 33634341, 2021). "Anti-tumor necrosis factor (TNF) therapy was determined to be useful for controlling several recalcitrant uveitides; IL-6 inhibitors also showed efficacy in refractory JIA-associated uveitis, Behcet’s uveitis and so on." (PMID 34054864, 2021). "Treatment of uveitis with anti-TNF-α antibodies reduces ocular inflammation." (PMID 34520511, 2021). "Evidence of the feasibility of using anti-TNF-α agents for uveitis management has increased." (PMID 34795583, 2021).